ALB (albumin)
Diseases named in the same sentence as ALB in open-access papers (continued):
Sharing a sentence is not in itself a finding about the gene and the disease.
Sepsis (continued). "Taken together, the current evidence suggests that albumin administration in patients with severe and advanced sepsis who have potential impairment of the protective effects of serum albumin may provide a survival benefit." (PMID 33287911, 2020). "The ROC curves showed that SIRT1 predicted 28-day mortality risk in sepsis patients, and its predictive value was not inferior to Scr, albumin, WBC, and CRP, while less than SOFA score and APACHE II score." (PMID 33263643, 2020). "Binding affinity of albumin to bilirubin decreases in sepsis; it is increased with the rise of body temperature and depends on the presence of other ligands which can compete with bilirubin for binding sites on albumin." (PMID 33033449, 2020). "Patients with sepsis-associated AKI had lower levels of albumin-adjusted free thiol levels compared to patients without sepsis." (PMID 33207555, 2020). "The characteristics of patients who developed sepsis included female sex, lower albumin, higher globulin, lower AGR (<1.5), preoperative fever, leukocytosis (WBC ≥ 10,000 cells/μL), positive urine culture, leukocyturia (≥50 cells/μL), and positive urine nitrite." (PMID 32655994, 2020). "This study began by observing senior clinicians performing an analogical reasoning for sepsis (a major life-threatening condition) with embeddings and posing search queries such as −sepsis +serum_albumin +fluid_therapy to discover treatments with therapeutic intent." (PMID 32759099, 2020). "Finally, age, male, APACHE II, sepsis, albumin, lymphocyte counts, Hb, creatinine, HbA1c and ISTH overt DIC on admission were regarded as independent risk factors for PIICS." (PMID 32824569, 2020). "In univariate analysis, increasing age, higher ASA-score, higher ECOG performance score, sepsis, cardiovascular morbidity, low albumin level, and surgery for indications other than obstruction (i.e., ischemia and perforation) were associated with increased risk of mortality." (PMID 32391145, 2020). "One emerging sepsis biomarker is the lactate to albumin (L/A) ratio." (PMID 33072780, 2020). "It is possible that low serum albumin level, anemia, and sepsis or severe infectious disease may be related to the development of hypovolemic outcomes resulting in decreased blood flow." (PMID 31827924, 2019). "The sepsis, CKD, and CKD-with-sepsis groups showed significant body weight loss and a lower serum albumin level than the control group (p < 0.01); the CKD-with-sepsis group showed the lowest body weight and serum albumin level." (PMID 31795376, 2019). "Sepsis also decreases serum concentrations of total cholesterol and albumin." (PMID 31086028, 2019). "As shown in a substudy of the ALBIOS trial, a multicenter, randomized controlled trial to compare the effect of human albumin and crystalloids versus crystalloids alone in patients with severe sepsis, PTX3-values had a tendency to decrease over time, even in cases of severe sepsis." (PMID 31798002, 2019). "The ratio of CRP to ALB (CRP/ALB) has also recently been used to predict the prognosis of patients with severe sepsis or septic shock, with an increased CRP/ALB ratio at the intensive care unit (ICU) admission being independently associated with increased mortality rates." (PMID 30297724, 2018). "Fourth, some other laboratory markers, such as procalcitonin, lactic acid, and albumin, which are associated with mortality in patients with severe sepsis, were not included in this study." (PMID 29915256, 2018). "This is a retrospective analysis of the ALBIOS study, a randomized controlled study conducted between 2008 and 2012 in 100 intensive care units in Italy comparing the administration of 20% albumin and crystalloids versus crystalloids alone in patients with severe sepsis or septic shock." (PMID 30261898, 2018).
Sepsis (continued). "For example, numerous combinations may be used in daily practice with regard to resuscitation fluids: blood and crystalloids (trauma), crystalloids early (post-operative hypovolemia), albumin late (sepsis)." (PMID 29789983, 2018). "In addition, the CRP/albumin ratio showed high values of 8.7 and 5.09, respectively, in patients with severe sepsis or septic shock." (PMID 29880755, 2018). "In a study on 334 adults with severe sepsis or septic shock, it was concluded that the C-reactive protein/albumin ratio at the time of discharge from the intensive care unit was correlated with the long-term prognosis (up to 90 days) after an episode of sepsis." (PMID 29267535, 2018). "In this study, we examined plasma metabolome, proteome and clinical features in a subset of patients with the most severe manifestation of sepsis, enrolled in the multicenter, randomized clinical trial ALBIOS (Albumin Italian Outcome Sepsis study, NCT007071225)." (PMID 29703925, 2018). "We hypothesized that fluid resuscitation with the novel Seplyte fluids would reduce the hepatic inflammatory response during early sepsis and that supplementing these fluids with albumin would enhance this reduction." (PMID 28105603, 2017). "As a negative acute phase protein, initial serum albumin was also independently associated with disease progression to severe sepsis and 30-day mortality in emergency medical patients, irrespective of the cause." (PMID 29147647, 2017). "As lactate and albumin levels evidence a divergent course as the development of sepsis progresses, a ratio between the two could serve as a novel and maybe better indicator for the prognosis of the patient." (PMID 28869492, 2017). "Fluid resuscitation is a crucial therapy for sepsis, and the use of balanced fluids and/or isotonic albumin may improve patient survival." (PMID 28105603, 2017). "Moreover, the surviving sepsis guidelines support the use of albumin in patients requiring large amounts of fluid for hemodynamic stabilisation." (PMID 28683810, 2017). "Low serum albumin (<35 g/L) is often observed in hospitalized elderly patients or patients with decompensated liver cirrhosis, malnutrition, nephrotic syndrome, diabetes, heart failure, cancer, and sepsis." (PMID 29147647, 2017). "Thus, the net effect of sepsis-associated reduced CBG and albumin levels is reduced cortisol delivery to local sites of inflammation." (PMID 27379022, 2016). "Evidence from well-designed network meta-analyses and clinical trials suggests that crystalloid fluids, particularly balanced solutions, seem to be the most advisable first choice, and albumin is equivalent or superior to other available fluids in severe sepsis and septic shock." (PMID 27313844, 2016). "We hypothesized that albumin may exert concentration-dependent effects on microvascular perfusion when used for fluid resuscitation during sepsis." (PMID 26942605, 2016). "Longer-term and more realistic models of sepsis, such as cecal ligation and puncture, could be more suitable for investigating the pleiotropic effects of albumin, particularly its anti-oxidant and anti-inflammatory properties." (PMID 26942605, 2016). "In HIV-infected patients, CD4 count and albumin levels negatively correlate with incidence of post-operative sepsis, whereas surgical infections and previous major surgical procedures positively correlated with the incidence of post-operative sepsis." (PMID 27747712, 2016). "In our patient cohort, serum albumin <3.5 g/dL and an ED triage diastolic blood pressure <52 mmHg independently predict early progression to severe sepsis or shock among ED patients with presumed sepsis." (PMID 26908009, 2016). "However, in patients with severe sepsis, S1P was distributed equally between apoM and albumin, indicating that during sepsis S1P is mainly lost from apoM." (PMID 26990127, 2016).
Sepsis (continued). "Pre-treatment of wild-type mice with apocynin prior to CLP-sepsis surgery similarly abrogated the septic increases in pulmonary microvascular/PMVEC EB-albumin permeability, PMVEC death (PI+) and apoptosis (TUNEL+), similar to the observations in septic NADPH oxidase-deficient mouse strains." (PMID 26376777, 2015). "Thus, these tissue albumin measurements provide evidence for lung, kidney, and liver endothelial dysfunction and associated microvascular leak in this ALI-sepsis model." (PMID 25959381, 2015). "The contribution that human albumin could make towards the maintenance of renal function in the course and treatment of severe sepsis and cirrhosis of the liver is the subject of this narrative review." (PMID 26136776, 2015). "Albumin and C-reactive protein (CRP) are considered as good diagnostic markers for sepsis." (PMID 26158725, 2015). "PMVEC apoptosis has been proposed in sepsis models, and could contribute to pulmonary microvascular albumin-permeability barrier dysfunction." (PMID 26376777, 2015). "However, when the aspiration insult was combined with sepsis, the recruitment of neutrophils and accumulation of albumin to the airspaces was actually reduced." (PMID 26423575, 2015). "In addition there are rare studies investigating the effects of different albumin levels on the disease severity and outcomes for adults with sepsis, especially surgical sepsis." (PMID 26557421, 2015). "However, few studies investigated the effects of different albumin levels on the prognosis of patients with surgical sepsis." (PMID 26557421, 2015). "Albumin levels were negatively correlated the prognosis of surgical sepsis when below about 23 g/L." (PMID 26557421, 2015). "In clinical conditions of increased capillary porosity, like sepsis, albumin and other proteins may reach the extravascular space and, consequently, πis rises and the flow of fluid increases." (PMID 25887223, 2015). "Thus, initial CRP and albumin levels were combined to ascertain their value as an independent predictor of 180-day mortality in patients with severe sepsis and septic shock." (PMID 26158725, 2015). "Similarly, another large trial involving 800 patients with sepsis in France resuscitated either with 20% albumin or normal saline, conducted by the EARSS study group, is yet to publish its results." (PMID 25180196, 2014). "The aim of the present study was to determine SAA, CRP and albumin concentrations in dogs with sepsis and pyometra and to evaluate whether these inflammatory markers are associated with length of postoperative hospitalization." (PMID 25430894, 2014). "Conversely, patients with sepsis seemed to have better outcomes with albumin." (PMID 25276346, 2014). "Therefore, if there is no significant advantage of albumin in reducing mortality rate, it is difficult to justify unrestricted use of albumin for resuscitation of patients with sepsis." (PMID 25474401, 2014). "As the unsolved, fundamental challenge in resuscitating severe sepsis and septic shock, it is recommended that albumin should be added to the initial resuscitation with crystalloid, and the application of hydroxyethyl starches was against given their role in renal injury." (PMID 25499187, 2014). "The aim of this study was to examine whether albumin reduced mortality when employed for the resuscitation of adult patients with severe sepsis and septic shock compared with crystalloid by meta-analysis." (PMID 25499187, 2014). "Generalized peritonitis is extremely critical and difficult to treat because the rapid spread of barium over the peritoneal cavity can lead to the exudation of a large volume of fluid and albumin, which results in hypovolemia and fecal contamination with consequent sepsis." (PMID 23955478, 2014). "Together, our results suggest that apoptosis of the pulmonary MVEC during sepsis may be a result of leukocyte activation, and in turn, may contribute to microvascular albumin leakage during sepsis." (PMID 24516666, 2014).
Sepsis (continued). "Our goal was to examine whether albumin reduced mortality when employed in the resuscitation of adult patients with severe sepsis and septic shock compared with crystalloid solutions and saline." (PMID 25499187, 2014). "Furthermore, there are settings where one fluid is clearly advantageous, such as sepsis patients with traumatic brain injury where albumin and hypotonic resuscitation fluids should be avoided." (PMID 25180196, 2014). "Subgroup analysis of the SAFE study suggested there may be a benefit in patients with severe sepsis (35% of whom had septic shock), with an adjusted odds ratio for death of 0.71 (95% CI, 0.52 to 0.97; P = 0.03) for albumin compared with saline." (PMID 25042164, 2014). "However, there is concern about which agent would improve the outcome of the patients with severe sepsis and septic shock, especially the comparison between albumin and crystalloid." (PMID 25499187, 2014). "Five studies were included in the analysis of albumin use in sepsis." (PMID 24222902, 2013). "The role of albumin resuscitation in sepsis remains challenging." (PMID 23601847, 2013). "The use of albumin resulted in no significant advantage in risk of death, encephalopathy, hyponatraemia, gastrointestinal bleeding, readmission, renal impairment, and sepsis/severe infection." (PMID 24222902, 2013). "• Sepsis is associated in its initial phase with a significant alteration in the composition of the GFB-associated glycocalyx, with loss of GFB perm-selectivity as documented by albumin leakage into urine." (PMID 22108136, 2011). "Serial monitoring of bedside urine albumin-creatinine measurement may potentially aid clinical assessment in the early identification of patients with sepsis that requires early targeted therapy." (PMID 20606905, 2010). "In a randomized clinical trial of 20 patients with acute lung injury due to trauma, pneumonia, sepsis and other insults, repeated administration of 25% albumin elevated plasma thiol concentration (p = 0.0001) and total antioxidant capacity (p = 0.033) compared with saline placebo." (PMID 18318896, 2008). "The marked decrease in serum albumin in patients with severe sepsis may lead to lower levels of TAC detected using the spectrophotometric method." (PMID 16507162, 2006). "Timing may be of critical importance because an accelerated plasma efflux of albumin was only observed during the early phase of sepsis in rats." (PMID 15774049, 2005). "Among these, CAR’s unique strength for sepsis-AKI lies in its direct and dual assessment of renal function (via creatinine, more specific to acute renal injury than BUN) and systemic inflammation/nutritional status (via albumin), which is central to the underlying pathophysiology." (PMID 41425961, 2025). "Early albumin administration may increase the risk of SA-AKI in sepsis patients without conferring a short-term survival benefit." (PMID 40841985, 2025). "Therefore, the significantly reduced concentrations of HDL and albumin in sepsis may reduce the t1/2 in serum and exacerbate the off‐target effects of 3,4‐cPP." (PMID 40470379, 2025). "However, there are limited studies on the lactate-to-albumin ratio (LAR) in sepsis." (PMID 40046181, 2025). "Notably, recent studies have suggested that early combination therapy with crystalloids and albumin in patients with sepsis, septic shock, or cardiogenic shock may confer a survival advantage over crystalloid therapy alone in the intensive care unit (ICU)." (PMID 41468394, 2025). "Flii showed a medium correlation with serum total protein and albumin levels, indicating that in sepsis, the loss of non-specific proteins might also be responsible for the decreased Flii concentrations." (PMID 41462865, 2025).
Sepsis (continued). "This study represents an initial attempt to explore whether key clinical parameters, such as the SIC score, serum albumin, and peripheral resistance, can be statistically integrated to reflect a shared pathophysiological process consistent with endothelial injury in sepsis." (PMID 40710030, 2025). "The usefulness of the L/A ratio as a predictor of mortality in sepsis has been investigated in pediatric populations and in adult populations, with generally favorable results and demonstrating better performance compared to lactate or albumin levels individually." (PMID 40283655, 2025). "Therefore guideline recommendations for albumin infusions in sepsis are weak." (PMID 40057738, 2025). "The decrease in ALB levels we observed in septic patients may be related to high levels of oxidative stress and capillary leak, which is consistent with the dysregulated host response at the core of sepsis pathophysiology." (PMID 40438354, 2025). "Similarly, serum albumin levels can be influenced not only by inflammation and nutritional status but also by factors such as fluid balance and liver function abnormalities, making it a less specific indicator of sepsis-related nutritional compromise." (PMID 40766844, 2025). "Therefore, our study aims to determine whether combined crystalloid and albumin therapy improves survival in ischemic stroke patients with sepsis in the ICU compared to crystalloid therapy alone." (PMID 41468394, 2025). "When the glycocalyx is degraded, as occurs in sepsis or inflammation, capillary permeability rises and the reflection coefficient declines, allowing colloids to extravasate almost as freely as crystalloids, thereby negating any theoretical advantage of albumin." (PMID 41247634, 2025). "Therefore, in the management of patients with extensive burns, timely supplementation with albumin and blood products may serve as an important strategy for preventing or mitigating sepsis." (PMID 40901002, 2025). "Moreover, the study only includes a single-time measurement of albumin and lacks data on sepsis." (PMID 39048942, 2024). "Our estimated cutoff value of >0.38 may be comparatively low due to the fact that the iTBI study population at the time of admission had lower CRP and higher albumin levels in comparison to, e.g., patients suffering from sepsis, pneumonia, or cancer, or patients after excessive abdominal surgery." (PMID 38791046, 2024). "Thus, albumin ≤23.11 g/L can be considered as an early indicator of sepsis prognosis." (PMID 38518050, 2024). "However, the effect of albumin on peripheral tissue perfusion in human sepsis remains poorly known." (PMID 38326920, 2024). "LASSO regression for the training cohort identified 12 variables associated with sepsis prognosis out of 45 clinical parameters: Age, Heart rate, AST, invasive ventilation treatment, renal replacement treatment, albumin, cerebrovascular disease, MHR, NLR, NHR, BUN, and Potassium." (PMID 38448999, 2024). "While serum albumin levels were only measured at admission in this study, conducting serial monitoring throughout the hospital stay could provide a more comprehensive understanding of sepsis prognosis." (PMID 38826606, 2024). "Moreover, albumin levels tend to decrease in patients with sepsis." (PMID 39583098, 2024). "Additionally, when combined with the SOFA score, which is widely used in diagnosing and assessing the severity of sepsis, and postoperative albumin levels, this comprehensive approach could further enhance the prediction of outcomes in GIP patients." (PMID 39709362, 2024). "The sPLA2–albumin dual serum assays may be useful in determining whether nutritional intervention effectively supports the more rapid recovery of appropriate immune responses in critically ill patients with sepsis." (PMID 39273360, 2024). "Serum albumin level may reflect the severity of sepsis and host status." (PMID 39459557, 2024).